RPE65 (retinoid isomerohydrolase RPE65)
Diseases named in the same sentence as RPE65 in open-access papers (continued):
Sharing a sentence is not in itself a finding about the gene and the disease.
Leber congenital amaurosis (continued). "Recently, AAV2-mediated gene transfer of RPE65 in patients affected with Leber's Congenital Amaurosis (LCA, type 2; OMIM 204100) achieved stable improvement of visual and retinal function." (PMID 21818300, 2011). "Pathogenesis in the Rpe65−/− mouse model of Leber's congenital amaurosis (LCA) is characterized by a slow and progressive degeneration of the rod photoreceptors." (PMID 19672311, 2009). "In 2008, the first successful clinical application of RPE65 gene augmentation therapy in patients with Leber congenital amaurosis or early-onset RP demonstrated both the safety and efficacy of this approach, leading to the first FDA-approved gene therapy for retinal disease." (PMID 41805095, 2026). "Current FDA-approved gene therapy approaches, such as the RPE65-targeted therapy approved for Leber congenital amaurosis, may have limited applicability to this Turkish cohort based on the genetic spectrum observed." (PMID 41562913, 2026). "A gene therapy (Luxturna) was approved in 2017 by the FDA for RPE65 mutation-associated retinal dystrophy in the treatment of Leber Congenital Amaurosis (LCA) by subretinal injection, but it is not based on RNA technologies." (PMID 41155961, 2025). "In experiments using Leber congenital amaurosis model mice, mother Rpe65−/− and Rpe65−/−/Nrl−/− mice received resveratrol via drinking water (120 μg/mL) for 20 days and 10–13 days, respectively, beginning on the day when the pups were at P5, and pups were then evaluated for cone degeneration." (PMID 40002341, 2025). "Gene replacement therapy for Leber’s amaurosis requires injection of RPE65 into the eye." (PMID 41304828, 2025). "Similarly, Luxturna was approved for Leber congenital amaurosis, a rare inherited retinal disease, and is designed to replace a defective RPE65 gene." (PMID 41235102, 2025). "In addition to the mouse models of RP, we tested TMB treatment with the Rpe65-/- mouse model of Leber Congenital Amaurosis (LCA)." (PMID 39009597, 2024). "RPE65 gene therapy (e.g., Luxturna) for Leber congenital amaurosis." (PMID 39439625, 2024). "However, while the AAV vector-based gene therapy drug was successful in treating patients with confirmed biallelic RPE65 mutation-associated Leber Congenital Amaurosis (LCA) and was approved by the FDA in 2017, clinical trials of gene therapy on XLRS patients have shown unpromising results." (PMID 37835784, 2023). "The list included genes associated with different forms of Leber congenital amaurosis, involved in disruptions in phototransduction (AIPL1), retinoid cycle (RDH12, RPE65), and transport across the photoreceptor connecting cilium (LCA5), as well as genes evidently interacting with AIPL1 (NUB1, AHR)." (PMID 38203368, 2023). "While gene replacement therapy has proven its safety and efficacy in treating recessive RPE65-associated Leber congenital amaurosis, such an approach is not suitable for dominant-negative diseases due to the need to silence the defective allele." (PMID 36421778, 2022). "Our proteomic data showed significant changes in the levels of proteins for retinitis pigmentosa (RPE65, RP2, MERTK, and RBP3), X-linked retinoschisis (RS1), CRB1-retinal dystrophy (CRB1), Usher syndrome (PCDH15), and Leber congenital amaurosis (RD3 and KCNJ13)." (PMID 36139394, 2022). "Furthermore, the first viral gene therapy (Luxturna; voretigene neparvovec) gained FDA approval in 2018 for treating Leber congenital amaurosis (LCA) type 2, caused by mutations in RPE65." (PMID 33652562, 2021). "The fervor of these ongoing efforts is motivated by the recent successful treatment of the RPE65-related form of Leber congenital amaurosis (LCA), a severe blinding disease, by a recombinant adeno-associated viral (AAV) vector that corrects the genetic deficit in those patients." (PMID 32120883, 2020).
Leber congenital amaurosis (continued). "Another model is the RPE-specific protein 65 kDA (RPE65) mutant mouse model, which is used to study Leber congenital amaurosis (LCA) and RP since the RPE 65 defect leads to a faulty isomerase which can no longer convert the chromophore necessary for rhodopsin to detect light." (PMID 26239347, 2015). "Clinical trials for RPE65-Leber congenital amaurosis (LCA) have demonstrated the ability to deliver therapeutic transgene to the retinal pigment epithelium (RPE) by subretinal injection thereby restoring retinal function and visually-evoked behavior to patients." (PMID 23637972, 2013). "Only one gene therapy drug is currently approved by FDA for Leber congenital amaurosis (LCA, MIM204000) caused by RPE65 mutations." (PMID 36975211, 2023). "However, unlike the success in treating RPE65 mutations in Leber Congenital Amaurosis, there have not been successful human clinical trials for treating CSNB." (PMID 37835784, 2023). "Luxturna® targets the RPE65 gene, which is primarily responsible for Leber congenital amaurosis (LCA)." (PMID 37763275, 2023). "In a mouse model of Leber congenital amaurosis (LCA) after gene therapy with AAV-delivered RPE65, a proteomic study found PRDX6 was significantly upregulated among 39 other proteins." (PMID 36274523, 2022). "As the sole isomerohydrolase in the RPE, defective RPE65 results in impaired all-trans to 11-cis isomerization and severely blinding disorders including autosomal recessive Leber congenital amaurosis (LCA), and dominant or recessive retinitis pigmentosa (RP)." (PMID 29696141, 2018). "Since the Leber congenital amaurosis (LCA2, with RPE65 mutation) clinical trial began and only one eye was treated each time, this raises the concern that an initial subretinal injection may affect the future therapeutic effect of later treatments in the contralateral eye of that patient." (PMID 19190735, 2009). "Biallelic mutations in the RPE65 gene (online mendelian inheritance in man (OMIM) * 180069) cause the most severe forms of IRD, namely, Leber congenital amaurosis (LCA) and early onset retinal dystrophy, with an estimated worldwide prevalence of 1.20–2.37 per 100,000." (PMID 38254722, 2024). "This individual was diagnosed with Leber congenital amaurosis at age 3.5 years, and at their last visit at age 8 years, fundus examination showed mild retinal pigmentary mottling and attenuated vessels, consistent with RPE65-associated retinopathy, with no signs of ABCA4-associated maculopathy." (PMID 38219857, 2024). "Mutations in the RPE65 and LRAT genes have been associated with Leber congenital amaurosis (LCA)." (PMID 37510362, 2023). "RPE65 is one of the first RPE-specific proteins to be linked to human IRDs, and examples of these disorders are Leber congenital amaurosis (LCA) and retinitis pigmentosa (RP), which are disorders that can be broadly characterized as blindness from birth or early childhood." (PMID 37510362, 2023). "All patients included in this report had confirmed biallelic RPE65 mutations and presented with the clinical picture of the most severe form of RPE65 IRD, Leber congenital amaurosis." (PMID 36672611, 2022). "Naturally occurring canine models exist for several IRDs, some of which have contributed to gene augmentation therapies in humans, such as the Rpe65 model for Leber congenital amaurosis (LCA), and the Pde6a and Pde6b models for autosomal recessive RP phenotypes." (PMID 34828377, 2021). "Lack of functional RPE65 can lead to blinding disease, such as retinitis pigmentosa or Leber’s congenital amaurosis and has been successfully targeted in gene-therapy." (PMID 40137287, 2025). "The treatment also improves rod pathway function in an Rpe65-/- mouse model of Leber congenital amaurosis but does not protect from cone degeneration." (PMID 39009597, 2024).
Leber congenital amaurosis (continued). "It includes Leber congenital amaurosis (LCA, about 5 % RPE65-IRD), early onset severe retinal dystrophy (EOSRD), and juvenile retinitis pigmentosa (about 1 % RPE65-IRD)." (PMID 39943983, 2025). "For example, in RPE65 gene augmentation therapy for Leber Congenital Amaurosis improved visual function can be detected in the absence of an ERG improvement both in human patients in phase I/II clinical trials, but also in the dog model when receiving a low dose of therapeutic vector." (PMID 28676737, 2017). "Interestingly, certain genes commonly associated with Leber congenital amaurosis/early-onset severe retinal dystrophy (LCA/EOSRD) in Western Europe, such as CEP290 and RPE65, were only minimally (CEP290) or not at all (RPE65) involved in the Chilean cohort." (PMID 38892339, 2024).
Retinal dystrophy (150 papers, 2009 to 2026). Retinal dystrophy is an abnormality of the retina associated with a hereditary process. "While gene-specific replacement therapies have achieved landmark success with voretigene neparvovec (Luxturna) for biallelic RPE65-associated retinal dystrophy, developing individual therapies for each genetic subtype remains impractical." (PMID 42074510, 2026). "A breakthrough in treating inherited retinal dystrophies, including some forms of RP, is gene therapy with Luxturna (voretigene neparvovec-rzyl), targeted at mutations in the RPE65 gene." (PMID 40869487, 2025). "All RPE65‐associated retinal dystrophy patients who have sufficient viable retinal cells with confirmed biallelic mutations in the RPE65 gene, including patients with UPiD, are eligible for VN therapy." (PMID 39835736, 2025). "Luxturna uses an adeno-associated viral (AAV) vector–mediated therapy for RPE65-associated retinal dystrophy." (PMID 40731809, 2025). "Following confirmation of efficacy and safety through an open‐labeled, randomized, controlled phase 3 trial, VN was approved for gene augmentation therapy in RPE65‐associated retinal dystrophy in 2017." (PMID 39835736, 2025). "Clinical observations suggest that gene therapy is effective from childhood through young adulthood in RPE65-associated retinal dystrophies." (PMID 41251530, 2025). "Maguire and co-workers reported that the therapeutic effects of voretigene neparvovec-rzyl (Luxturna®) were maintained for up to four years in patients with RPE65-associated retinal dystrophy." (PMID 40731809, 2025). "In the phase 3 clinical trial, 29 patients with RPE65-associated retinal dystrophy received subretinal injections of Luxturna." (PMID 40731809, 2025). "FECD develops due to toxic gain-of-function after trinucleotide repeat resulting in protein misfolding, which is different to the retinal pigment epithelium (RPE) loss of function in the RPE65-mediated inherited retinal dystrophy." (PMID 41153439, 2025). "Targeting inherited retinal dystrophy brought on by mutations in the RPE65 gene, one of the most well-known treatments is Voretigene neparvovec-rzyl (marketed as Luxturna)." (PMID 40725503, 2025). "Our study presents an automated DL-based approach for the precise evaluation of retinal changes in RPE65-associated inherited retinal dystrophy (RPE65-IRD) including treatment-related effects using OCT (SD-OCT) data." (PMID 39745677, 2025). "It includes patients with confirmed biallelic RPE65 mutation-associated inherited retinal dystrophy who meet the approved indications for treatment." (PMID 40869487, 2025). "This adeno‐associated virus (AAV) gene therapy is delivered via subretinal injection to treat patients with retinal dystrophy due to biallelic pathogenic variants in RPE65." (PMID 39039945, 2025). "Advances in adeno-associated virus (AAV)-based gene therapy have demonstrated safety and efficacy in treating various IRDs, as highlighted by the FDA approval of voretigene neparvovec-rzyl (Luxturna) for RPE65-associated retinal dystrophy." (PMID 39598155, 2024). "Summary of Japanese patients with inherited retinal dystrophy, who carry biallelic variants in the RPE65 gene (NM_000329.3)." (PMID 39359914, 2024). "Individuals carrying biallelic RPE65 mutations, which are associated with retinal dystrophy, experience a gradual loss of vision, typically emerging during childhood or adolescence." (PMID 39245805, 2024). "Such variants in RPE65 account for approximately 11.4% of cases in early-onset retinal dystrophies in Western populations." (PMID 39359914, 2024). "NCT00999609 used subretinal-injected AAV2-encoded RPE65 to treat retinal dystrophy in 21 patients, where two of the cases showed adverse drug reactions, and one individual showed convulsions." (PMID 38247731, 2024). "The success of gene therapy in addressing RPE65‐associated retinal dystrophy is exemplified by Luxturna® (Voretigene neparvovec)." (PMID 39245805, 2024).
Retinal dystrophy (continued). "This groundbreaking gene therapy utilizes an AAV2 vector and is designed for individuals experiencing vision loss due to inherited retinal dystrophy stemming from confirmed biallelic RPE65 mutations." (PMID 39245805, 2024). "LRS was conducted in five inherited retinal dystrophy (IRD) patients harboring a monoallelic variant in RPE65 that remained uncharacterized after clinical exome sequencing (CES)." (PMID 39469149, 2024). "In Japan, inherited retinal dystrophy caused by biallelic variants of the RPE65 gene is exceedingly rare." (PMID 39359914, 2024). "Currently there is only one approved treatment for a specific and rare early onset retinal dystrophy called RPE65-associated retinal dystrophy, this has been approved by United States Food and Drug Administration (FDA) and European Medicines Agency (EMA)." (PMID 37226218, 2023). "A pivotal Phase III clinical trial demonstrated a substantial visual improvement in a twelve-month period among patients identified with biallelic RPE65 gene mutations associated with retinal dystrophy, subsequent to Luxturna therapy." (PMID 38145048, 2023). "Luxturna is an adeno-associated virus vector carrying the RPE65 gene for RPE65-associated retinal dystrophies." (PMID 37298674, 2023). "The recent trial of antisense oligonucleotide treatment with Sepofarsen for RPE65 mutation-associated retinal dystrophy has demonstrated risks such as cataractogenesis, retinal thinning, and cystoid macular changes." (PMID 37762657, 2023). "Therapeutic gene therapy has been approved for correction of the genetic defect carried by patients with a retinal pigment epithelial 65-kDa protein (RPE65) mutation associated with retinal dystrophy." (PMID 36905120, 2023). "In December 2017, following a successful phase III randomized, controlled, open-label study, Luxturna became the first FDA-approved ocular gene therapy for RPE65-associated retinal dystrophy." (PMID 37762059, 2023). "It is useful to consider what clinical outcome measures and endpoints have been used previously and worked well, such as those used in gene therapy treatment for RPE65-associated retinal dystrophy." (PMID 37762657, 2023). "RPE65-associated retinal dystrophy presents as an early onset retinal dystrophy, presenting before age five with severe visual impairment due to central atrophy." (PMID 37762657, 2023). "Antisense oligonucleotides have shown promise in both in vitro and in vivo models of RPE65 mutation-associated retinal dystrophy." (PMID 37762657, 2023). "The third most frequent genetic subgroup contained 15 patients with RPE65-associated retinal dystrophy (15/105, 14%, age 9–51 years; 10 female, 5 male)." (PMID 37240262, 2023). "Retinal dystrophy, caused by biallelic RPE65 mutation, leads to progressive vision loss and eventually blindness." (PMID 37895887, 2023). "Another FDA-approved AAV-based gene therapy medication is Luxturna, which is intended for the treatment of retinal dystrophy caused by biallelic mutations in the RPE65 gene (an enzyme of retinal cells involved in light-sensitive pigment regeneration)." (PMID 36899921, 2023). "Voretigene neparvovec is a gene therapeutic agent for treatment of retinal dystrophies caused by bi-allelic RPE65 mutations." (PMID 33472769, 2022). "As the first US FDA approved gene therapy for monogenic diseases, LUXTURNA® received approval in 2017 in the United States and subsequently in Canada and Australia in 2020 for treating Biallelic RPE65 mutation‐associated retinal dystrophy." (PMID 35079633, 2022). "It is used for RPE65 mutation-based retinal dystrophies, namely, LCA2 and a subgroup of autosomal recessive RP." (PMID 35911417, 2022). "Bi-allelic pathogenic variants in RPE65 give rise to an early-onset retinal dystrophy, often from birth, for which gene therapy is now available and licensed in many countries." (PMID 35704304, 2022).